PRMT5 (protein arginine methyltransferase 5)
Diseases named in the same sentence as PRMT5 in open-access papers (continued):
Sharing a sentence is not in itself a finding about the gene and the disease.
tumor (continued). "However, the large number of differentially expressed genes could suggest that PRMT5 interacts with another epigenetic pathway to alter a range of tumour relevant pathways." (PMID 38172189, 2024). "Therefore, PRMT5 mainly functions as a tumor-promoting factor." (PMID 39424627, 2024). "In addition, Western blot and quantitative real-time PCR analysis showed that the expression levels of PRMT5 and circRHOT1 were decreased in tumor tissues of the si-circRHOT1 group compared with the si-NC group, while the expression level of miR-204-5p was increased." (PMID 37924099, 2023). "High expression levels of PRMT5 were positively correlated with its substrate H4R3me2s and cell proliferation marker Ki67, with a correlation coefficient (R) value of 0.9129 and 0.9797, respectively, depicting the cell proliferation and tumor-promoting function of PRMT5." (PMID 36797243, 2023). "Accordingly, we hypothesized that the tumor‐suppressive activity of MTAP is mediated through the MTA/PRMT5/protein dimethylation axis, and thus we identified those differentially symmetrically dimethylated proteins in response to MTAP alteration by mass spectrometric analyses." (PMID 35766227, 2022). "Additionally, PRMT5 inhibition in vivo exhibited modest anti-tumor activity." (PMID 36167829, 2022). "In addition, it is needed to examine in the future whether PRMT5 functions as a tumor suppressor in other tumor-type formations using Prmt5 knockout mouse models." (PMID 35864961, 2022). "PRMT5 inhibitors might exert beneficial effects on tumor cytotoxicity but also disrupt the tumor immunosurveillance, possibly explaining why current PRMT5 inhibitors have no selectivity for MTAP‐loss tumors but instead are broadly anti‐proliferative." (PMID 35766227, 2022). "Protein arginine methyltransferase 5 (PRMT5) is an attractive molecular target in anticancer drug discovery due to its extensive involvement in transcriptional control, RNA processing, and other cellular pathways that are causally related to tumor initiation and progression." (PMID 35744905, 2022). "Moreover, PRMT5 expression was higher in stem/progenitor cells compared to total peripheral blood leukocytes, suggesting that this gene may have a major pro-tumour role in the LSC compartment." (PMID 36230624, 2022). "Furthermore, SRSF2 and 3 showed the strongest correlation with PRMT5 in LIHC tumor specimens." (PMID 36499164, 2022). "In addition to the propagation of glial cell lineage, PRMT5 is hypothesized to be involved in tumor angiogenesis." (PMID 33440687, 2021). "Moreover, countless studies have demonstrated that PRMT5 promotes tumor progression." (PMID 34476262, 2021). "PRMT5 may act as a tumor-inducing agent in ESCC by modulating LKB1/AMPK/mTOR pathway signaling." (PMID 34124017, 2021). "Moreover, knocking down PRMT5 could weaken the tumor growth and lung metastasis in vivo while upregulating the LKB1 expression and the p-AMPK level and downregulating the p-mTOR expression." (PMID 34124017, 2021). "In addition, the knock-down of PRMT5 could inhibit tumor growth and lung metastasis by the up-regulation of LKB1 and p-AMPK, and the down-regulation of p-mTOR." (PMID 34513846, 2021). "Moreover, knocking down PRMT5 could weaken the tumor growth and lung metastasis in vivo with upregulating the LKB1 expression and the p-AMPK level and downregulating the p-mTOR expression." (PMID 34124017, 2021). "Moreover, knockdown of PRMT5 significantly suppressed tumor growth, which could be reversed by myr-AKT1." (PMID 34103528, 2021). "Moreover, in an in vitro co-culture system, knockdown of PRMT5 in tumor cells could directly enhance the expression of IFN-γ, TNF-α and granzyme B in T cells." (PMID 34522232, 2021).
tumor (continued). "Importantly, the SDMA mark was significantly reduced in the xenograft tissues of mice treated with LLY-283 as compared to the vehicle-treated mice, suggesting that the reduction of tumor size and concomitant increase in survival are due to the disruption of the enzymatic function of PRMT5." (PMID 33579912, 2021). "Interestingly, the subcellular localization and role of PRMT5 vary with the tumor type." (PMID 33060569, 2020). "In this study, we further elucidated the downstream signaling pathway using RNA-seq analysis; the pathway analysis of the gene expression profiling indicated that the PRMT5-mediated tumor growth and metastasis could be partially attributed to the activation of Wnt/β-catenin signaling pathway." (PMID 33060569, 2020). "Interestingly, PRMT5 levels and activity is reported to be elevated in several tumor cells and abnormal PRMT5 functions may contribute to some aspects of the malignant phenotype." (PMID 30800128, 2019). "Thus, PRMT5 primarily functions as a tumor-promoting factor." (PMID 30922330, 2019). "Experiments that solidify the importance of interaction between PRMT5 and PDCD4 revealed that when either protein is mutated, the tumor promoting activity of the pair is lost, indicating that PRMT5-mediated PDCD4 methylation is crucial for enhanced tumor growth." (PMID 30613353, 2018). "Our study demonstrating that PRMT5 depletion in an established tumour can reduce stem cell frequency is highly significant for the patient, as targeting this enzyme in conjunction with standard chemotherapies, could lead to eradication of all tumours cells, thus preventing relapse." (PMID 29876520, 2018). "Even though PRMT5 has been shown to promote the tumor progression and radioresistance of NPC, the role of PRMT5 in chemo-resistance in NPC has yet to be determined." (PMID 41513606, 2026). "In contrast, second‐generation PRMT5 inhibitors selectively bind the PRMT5–MTA complex and preferentially target MTAP‐deleted tumour cells." (PMID 41537447, 2026). "Clinically, PRMT5 and WDR77 expression in tumor-infiltrating T cells are negatively correlated with PDCD1 expression and renders tumors resistant to PD-1-targeted immunotherapy." (PMID 41623183, 2026). "We found that MYC, E2F1, and EIF4E are all positively correlated with PRMT5 and KRAS with an R-value > 0.70 and a p-value < 0.01 in CRC patient tumor samples." (PMID 40864819, 2025). "PRMT5 ensures proper splicing of full-length, catalytically active Tip60 (Tip60α), a critical driver of MCC tumorigenesis and tumor maintenance." (PMID 40846633, 2025). "By combining PRMT5 inhibitor with anti-PD1 therapy, significant tumor regression and CD4+ and CD8+ upregulation were demonstrated in vivo." (PMID 41439984, 2025). "Through a series of functional studies conducted both in vivo and in vitro, we demonstrated in our study that the PRMT5–meR316-ALKBH5–CD276 axis promotes CRC carcinogenesis and revealed that meR316-ALKBH5 expression in CRC affects tumor immune evasion." (PMID 39781264, 2025). "This epigenetic rewiring can shift the balance between oncogenic and tumor-suppressive transcriptional networks, sensitizing MTAP-deleted cells to further perturbation of PRMT5 or its upstream regulator MAT2A." (PMID 41465382, 2025). "The expression of PRMT1, PRMT3, PRMT4, PRMT5, and PRMT7 was elevated in tumor samples compared to normal tissue, while PRMT2, PRMT8, and PRMT9 were decreased." (PMID 40399547, 2025). "To summarize our findings concisely: we have uncovered a novel mechanism through which PRMT5 promotes tumor growth, namely by regulating CXCL10 expression within tumor cells while facilitating recruitment of T cells via interaction between CXCL10 and CXCR3." (PMID 41463372, 2025). "(G) Hematoxylin and eosin stain for tumor tissues obtained from mice of Prtm5-/-, ABC-Myc::Prmt5+/+, ABC-Myc::Prmt5+/-, and ABC-Myc::Prmt5-/-." (PMID 40326560, 2025).
tumor (continued). "In another study involving mouse models of liver HCC tumors, PRMT5 inhibition promoted lymphocyte infiltration and induced major histocompatibility complex II (MHC II) expression in the tumor microenvironment." (PMID 41439984, 2025). "In esophageal squamous cell carcinoma, PRMT5 enhances MMP2 and MMP9 expression via the LKB1/AMPK/mTOR axis, promoting tumor growth and metastatic dissemination." (PMID 41204384, 2025). "In laryngeal cancer, PRMT5 activates the WNT4/β-catenin axis to upregulate EMT markers and MMPs, promoting tumor growth and lymph node metastasis." (PMID 41204384, 2025). "In MYC-driven tumors, where MYC amplifies RNA production, MYC-induced PRMT5 maintains efficient splicing by preventing exon skipping in transcripts like EP400, which is essential for tumor progression." (PMID 40846633, 2025). "AMG 193 is an MTA-cooperative PRMT5 inhibitor in vitro, AMG 193 preferentially inhibited the MTA-bound PRMT5 enzyme in tumor cells with MTAP deletion." (PMID 41465382, 2025). "Further, there was a highly significant correlation between an amplified MYCN gene, and levels of PRMT5 and E2F1 gene expression in the tumour tissue." (PMID 39021294, 2025). "We next used the GEPIA database to determine which proteins have an expressional correlation with PRMT5 and KRAS in CRC patient tumor samples." (PMID 40864819, 2025). "Both PRMT1 and PRMT5, members of the protein arginine methyltransferase (PRMT) family, play crucial roles in tumor development." (PMID 40393971, 2025). "We demonstrated that PRMT5-mediated meR316-ALKBH5 promotes CD276 messenger RNA (mRNA) stability through m6A modification, thereby enhancing CRC tumor immune evasion both in vitro and in vivo." (PMID 39781264, 2025). "MTAP deletion in tumor cells leads to the accumulation of MTA in the microenvironment, which negatively impacts PRMT5 activity in T cells, as elevated MTA levels suppress its function." (PMID 39983717, 2025). "These proteins are shown to interact with both PRMT5 and KRAS in STRING, are overexpressed in CRC tumor samples, and show positive gene expression correlations with PRMT5 and KRAS in patient data." (PMID 40864819, 2025). "In tumours where MYCN, PRMT5 and E2F1 are expressed at lower levels and splicing activity is similarly reduced, we suggest that other PRMT5 independent mechanisms contribute to the malignant phenotype." (PMID 39021294, 2025). "In the dual-knockdown (PRMT5 and CXCR3) model, while the tumor cells still have PRMT5 knockdown, the host’s T cells lack the CXCR3 receptor." (PMID 41463372, 2025). "JNJ-64619178, inhibitor of PRMT5, leads to the inhibition of symmetric arginine dimethylation of SMD1/3 proteins, core components of the spliceosome in the tumor and alters aberrant splicing by suppressing PRMT5 enzymatic activity." (PMID 40282505, 2025). "MAT2A indirectly enhances the methylation of PRMT5 by promoting the production of SAM, which is closely related to the tumor progression of liver cancer and colorectal cancer." (PMID 40240755, 2025). "In this study, we demonstrated that the triple combination of a PRMT5 inhibitor, CPT‐11, and αTIGIT exhibited superior anti‐tumor efficacy with minimal toxic side effects, and this synergistic effect successfully reactivated T cell immunity." (PMID 40344511, 2025). "Our analysis revealed significant upregulation of both PRMT5 and WDR77 mRNA levels in tumor samples compared to normal samples from patients with HNSCC." (PMID 39594744, 2024). "In the same study, the PRMT5 inhibitor C220 reduced the transcription and altered the splicing pattern of selected DDR genes and enhanced tumor cell sensitivity to the DNA damaging chemotherapeutic agents cisplatin, olaparib and 5-FU." (PMID 39068290, 2024). "Remarkably, knockdown or pharmaceutical inhibition (using EPZ015666) of PRMT5 inhibited the cell cycle progression and cell proliferation of KSHV latently infected tumor cells." (PMID 39255317, 2024).
tumor (continued). "PRMT5 has been shown to facilitate EMT in PDAC cells via the EGFR/AKT/β-catenin pathway, indicative of its involvement in tumor metastasis." (PMID 38612768, 2024). "More importantly, as our model illustrates, we showed that PRMT5-activated FXR1 is intricate in controlling the mRNA expression of its targets, playing both tumor-activating and tumor-suppressive roles." (PMID 38709899, 2024). "In NDRG2low ATL, cytoplasmic PRMT5 enhanced HSP90A chaperone activity via arginine methylation, leading to tumour progression and the maintenance of oncogenic client proteins." (PMID 38474089, 2024). "Weekly BLI TBL2 Acts as a Scaffold to Promote the Interaction Between PRMT5 and WDR77(Bioluminescence imaging) showed higher tumor loads in the TBL2‐overexpression group and lower tumor loads in the TBL2‐silenced group." (PMID 39499734, 2024). "In the present study, we also found that methylation of STAT3 by PRMT5/MEP50 in NSCLC cells is important for its transcriptional activity, for the generation and maintenance of CSCs, and for tumour growth in mice." (PMID 38760429, 2024). "For example, protein arginine methyltransferase 5 (PRMT5) inhibitor EZP015556 effectively inhibited both methylthioadenosine phosphorylase (MTAP)- and MTAP+ tumor organoids, both of which were hallmarked by high 5'-methylthioadenosine (MTA) levels." (PMID 38250041, 2024). "Thus, using a PRMT5 inhibitor in G4 astrocytomas may help in tumor regression." (PMID 38827324, 2024). "However, inhibiting the PRMT5 activity may assist in suppressing tumor growth in both cases." (PMID 38827324, 2024). "Knockdown of PRMT5 in the pancreatic cancer cell lines MIA-PaCa 2 and SW1990 reduces the viability and colony formation capacity of the cells in vitro and the tumor volume in xenograft nude mouse models." (PMID 38612768, 2024). "To further determine the effect of depleting PRMT5 and WDR77 in SCC development in the in vivo context, we injected 5 × 104 sgNeg, sgPRMT5, and sgWDR77 cells subcutaneously into nude mice to generate tumor xenografts." (PMID 39594744, 2024). "Alternatively, in tumor cells, MP is phosphorylated at T850 by ROK, and its diphosphatase activity on PRMT5 is inhibited, leading to the hyperphosphorylation of PRMT5 and increased H4R3me2s." (PMID 37928266, 2023). "PRMT5 was also suggested to regulate MHC II expression by histone methylation at the promoters of CD74 and CIITA, therefore affecting how tumours present to the immune system." (PMID 37795443, 2023). "Compared with T1-44, a selective inhibitor of PRMT5 activity, the combination of T1-44 with the TGF-β1 signaling inhibitor Vactosertib significantly reduced tumor size and surrounding tissue invasion and significantly improved long-term survival." (PMID 36765032, 2023). "The ability to unlock their expression through pharmacological manipulation of PRMT5 and E2F1 activity enables what is potentially a powerful therapeutic approach to control the immunogenicity of tumour cells." (PMID 36841868, 2023). "Following the concepts of synthetic lethality, when MTAP is lost in a tumor cell, MTA will build up inside the cell leading to more suppression of PRMT5, thereby increasing their vulnerability to inhibition." (PMID 36913304, 2023). "Two recent reports have demonstrated that PRMT5 inhibition impairs DNA repair, enhances radiosensitivity in multiple CRPC cell lines, and prevents RT-induced neuroendocrine differentiation and tumor growth in CRPC-AR tumor models." (PMID 38201511, 2023). "Of note, only one tumor expressed a high level of ERα/SDMA (number of dots/cell = 3), confirming that PRMT5 appears to be the best predictive marker of Tam sensitivity." (PMID 37458145, 2023). "In this review, we examine the current understanding of therapeutic vulnerabilities intrinsic to MTAP-negative tumours, focusing on MAT2A and PRMT5, which are receiving increasing attention in clinical development." (PMID 37795443, 2023).
tumor (continued). "Multiple PRMT5 inhibitors have been developed, such as GSK3326595, JNJ-64619178, and MRTX1719, all of which significantly suppressed tumor growth in preclinical models and are being currently tested in clinical trials." (PMID 37173967, 2023). "PRMT5 regulates antigen presentation by controlling NLRC5 expression, which regulates the expression of MHC class I genes, and the inhibition of PRMT5 expression leads to the increased expression of surface MHC class I and tumor cell recognition." (PMID 38136558, 2023). "Because PRMT5‐mediated Rbfox2 methylation is required for Rbfox2 ubiquitination and stabilization by FBXO7, we next explored the potential synergistic effects of FBXO7 silencing plus PRMT5 inhibition on GSC self‐renewal and tumor growth." (PMID 37822160, 2023). "Based on TCGA RNAseq data, a high expressional correlation between PRMT5 and APE1 was found in OSCC tumor tissues." (PMID 37887269, 2023). "PRMT5 in EMT: PRMT5 catalyzes the methylation of arginine on H2AR3, H4R3, and H3R8, and acts primarily as a tumor-promoting factor." (PMID 36902253, 2023). "One of these is PRMT5, a type II PRMT enzyme which has been shown to play a role in tumour development and progression in solid cancer." (PMID 35757005, 2022). "The tumor weight in the Ov-CUL4A group was also greatly larger than that in the Ov-NC group, and PRMT5 knockdown greatly inhibited the growth of tumor weight." (PMID 35333690, 2022). "Our results reveal that pharmacologic or genetic PRMT5 inhibition blocks the expression of SNAIL, TWIST, and ZEB1 and almost completely blocks metastases in aggressive in vivo tumor models." (PMID 35803962, 2022). "Along with high levels of methylation of PRMT4, PRMT5, PRMT7, and hnRNPA1 in tumor samples, changes in gene alternative splicing were observed, such as those for PPARA, SREBF2, RAB27B, and WDPCP in BRCA, CRC, and PC samples." (PMID 33782401, 2021). "The majority of CRC biopsies displayed PRMT5- and CDKN2B-positive staining in both cytoplasmic and nuclei of tumor cells, whereas EZH2 was apparently expressed in the nuclei of tumor cells." (PMID 33664859, 2021). "Furthermore, with the analysis of histological and IHC in tumor sections, the levels of TUNEL and Ki-67 were lower in the PRMT5 siRNA group than the control siRNA, which indicated that knocking down PRMT5 could inhibit the tumor growth and induce the tumor cell apoptosis in vivo." (PMID 34124017, 2021). "In this study, our experiment also demonstrated that overexpression of PRMT5 can promote the invasion, migration, and proliferation of OSCC tumor cells." (PMID 34476262, 2021). "PRMT5 epigenetically suppresses RBL2, a member of the retinoblastoma tumor suppressor family, and indirectly enhances RB1 phosphorylation, resulting in the activation of the polycomb repressor complex PRC2 and Cyclin D137." (PMID 34006904, 2021). "Our genome-wide analysis indicated that the Snail/PRMT5/NuRD(MTA1) complex play important roles in cell migration and tumor cell invasion." (PMID 33953349, 2021). "Only the fold change in DDAH2, ODC1, and PRMT5 expression differed significantly with overall TNM stage, with tumor-to-adjacent ratio decreasing in a stepwise manner along with increasing stage." (PMID 32872669, 2020). "After examining the RNA-Seq data of CRC patients from the TCGA database using the GEPIA website, we found that PRMT5 expression is in fact strongly positively correlated (p < 0.005, R = 0.81) with KRAS expression in CRC patient tumor samples." (PMID 32731506, 2020). "Here we discuss the function of PRMT5, a member of the nine-member PRMT family, in controlling oncogenic processes including tumor intrinsic, as well as extrinsic microenvironmental signaling pathways." (PMID 32743345, 2020). "Our results show for the first time that PRMT5, in part through the PRMT5-E2F1 axis, influences tumour cell migration and invasion, and further suggest that this relationship is significant in human disease." (PMID 32709847, 2020).